DEFA1B (defensin alpha 1B)
Description:
Effector molecule of the innate immune system that acts via antibiotic-like properties against a broad array of infectious agents including bacteria, fungi, and viruses or by promoting the activation and maturation of some APCs. Interacts with the essential precursor of cell wall synthesis lipid II to inhibit bacterial cell wall synthesis. Inhibits adenovirus infection via inhibition of viral disassembly at the vertex region, thereby restricting the release of internal capsid protein pVI, which is required for endosomal membrane penetration during cell entry. In addition, interaction with adenovirus capsid leads to the redirection of viral particles to TLR4 thereby promoting a NLRP3-mediated inflammasome response and interleukin 1-beta (IL-1beta) release. Induces the production of proinflammatory cytokines including type I interferon (IFN) in plasmacytoid dendritic cells (pDCs) by triggering the degradation of NFKBIA and nuclear translocation of IRF1, both of which are required for activation of pDCs.
Synonyms: HP-1; HP1; HNP-1
Gene: Protein-coding gene on chromosome 8 (6,996,766 to 6,999,202, reverse strand). Ensembl gene ENSG00000240247.
Subcellular location: Secreted
Pathways (Reactome):
Immune System: Alpha-defensins; Defensins; Neutrophil degranulation
Gene Ontology:
Molecular function: pore-forming activity; protein binding
Biological process: antibacterial humoral response; antimicrobial humoral immune response mediated by antimicrobial peptide; defense response to Gram-positive bacterium; estrogen receptor signaling pathway; innate immune response in mucosa; killing of cells of another organism; T cell chemotaxis; chemotaxis; defense response to Gram-negative bacterium; disruption of plasma membrane integrity in another organism; immune response; innate immune response; defense response
Cellular component: extracellular exosome; extracellular region; azurophil granule lumen; Golgi lumen
Homologues: Orthologues: chimpanzee DEFA1 (96% identical), macaque DEFA1B (84% identical), rabbit MCP-1 (44% identical), rat Defa5 (36% identical), mouse Defa2 (35% identical), mouse Defa20 (35% identical), mouse Defa32 (35% identical), mouse Defa33 (35% identical), mouse Defa34 (35% identical), mouse Defa5 (35% identical), rat Np4 (35% identical), mouse Defa17 (34% identical), and 30 more. Paralogues in human: DEFA1 (100% identical), DEFA3 (99% identical), DEFA6 (49% identical), DEFA5 (48% identical), DEFA4 (46% identical).
Diseases named in the same sentence as DEFA1B in open-access papers:
DEFA1B is named in the same sentence as 12 diseases in open-access papers, as found by Europe PMC text mining. Sharing a sentence is not in itself a finding about the gene and the disease. The quoted sentences say what the papers report.
COVID-19 (3 papers, 2022 to 2025). A disease caused by infection with severe acute respiratory syndrome coronavirus 2. "The COVID-19 dataset revealed CAMP (AUC: 0.692), LTF (AUC: 0.764), DEFA1B (AUC: 0.701), SAMD9(AUC: 0.786), GBP1(AUC: 0.757), DDX60 (AUC: 0.802), DEFA4 (AUC: 0.763), and OAS3(AUC: 0.801) that exhibited superior diagnostic capabilities." (PMID 38115996, 2023).
influenza (2 papers, 2021 to 2024). An acute viral infection of the respiratory tract, occurring in isolated cases, in epidemics, or in pandemics; it is caused by serologically different strains of viruses (influenzaviruses) designated A, B, and C, has a 3-day incubation period, and usually lasts for 3 to 10 days. "In comparison, three patients had high activation of only a subset of influenza-connected genes PRTN3, LTF, PGLYRP1, DEFA1B, DEFA1, DEFA4, ELANE, and MPO." (PMID 34335605, 2021).
Graves ophthalmopathy (1 paper, 2024). An autoimmune disorder of the EYE, occurring in patients with Graves disease. "The alpha-defensins DEFA1, DEFA1B, and DEFA3 are overexpressed in orbital adipose tissue from patients with Grave’s ophthalmopathy." (PMID 38668354, 2024).
pneumonia (1 paper, 2013). An acute, acute and chronic, or chronic inflammation focally or diffusely affecting the lung parenchyma, caused by an infection in one or both of the lungs (by bacteria, viruses, fungi, or mycoplasma.). "The top 50 over-abundant transcripts in pneumonia were dominated by antimicrobial neutrophil-related genes e.g ELANE, DEFA1B, MMP8, CAMP, DEFA3, DEFA4, MPO, LTF." (PMID 23940611, 2013).
cancer (1 paper, 2025). A tumor composed of atypical neoplastic, often pleomorphic cells that invade other tissues. "The defensin family genes (DEFA1, DEFA1B, DEFA3) and CD177, typically linked to neutrophil function, may indicate the involvement of innate immunity in cancer development." (PMID 40227838, 2025).
tumor (1 paper, 2024). "The DEFA1B gene belongs to the α-defensin subgroup, which is known to promote tumor cell proliferation, contributing to tumor progression and invasiveness, as well as influencing tumor microenvironment due to their chemotactic properties (CD4+, CD8+, immature DC, monocytes)." (PMID 38398111, 2024).
DEFA1B also shares sentences with these, for which no sentence is quoted: co-infection (1 paper); plague (1); preeclampsia (1); prostate carcinoma (1); schizophrenia (1); tuberculosis (1).